DUSP12 (dual specificity phosphatase 12)
Description:
Dual specificity phosphatase; can dephosphorylate both phosphotyrosine and phosphoserine or phosphothreonine residues. Can dephosphorylate glucokinase (in vitro) (By similarity). Has phosphatase activity with the synthetic substrate 6,8-difluoro-4-methylumbelliferyl phosphate and other in vitro substrates.
Synonyms: YVH1; DUSP1
Tractability: PROTAC: ubiquitination databases record sites on it; its protein half-life has been measured.
Gene: Protein-coding gene on chromosome 1 (161,749,758 to 161,757,238, forward strand). Ensembl gene ENSG00000081721.
Subcellular location: Nucleus; Cytoplasm, cytosol
Subcellular location (Human Protein Atlas): Nucleoplasm
Gene Ontology:
Molecular function: phosphatase activity; protein binding; zinc ion binding; protein serine/threonine phosphatase activity; protein tyrosine phosphatase activity; protein tyrosine/serine/threonine phosphatase activity; kinase binding; phosphoprotein phosphatase activity
Biological process: dephosphorylation; protein modification process
Cellular component: cytoplasm; nucleoplasm; nucleus; cytosol
Genetic constraint (gnomAD): Loss-of-function variants: 24 observed, 35.72 expected, observed/expected ratio (o/e) 0.67, 90% interval 0.49 to 0.94. The upper end of that interval is the gene's LOEUF score, 0.94, which puts it in group 4 of 6, group 1 being the genes least tolerant of losing a copy. Missense variants: 388 observed, 434.03 expected, observed/expected ratio (o/e) 0.89, 90% interval 0.82 to 0.97. Synonymous variants: 150 observed, 157.43 expected, observed/expected ratio (o/e) 0.95, 90% interval 0.83 to 1.09.
Homologues: Orthologues: chimpanzee DUSP12 (100% identical), rabbit DUSP12 (86% identical), dog DUSP12 (85% identical), pig DUSP12 (85% identical), guinea pig DUSP12 (84% identical), mouse Dusp12 (84% identical), rat Dusp12 (83% identical), tropical clawed frog dusp12 (55% identical), zebrafish dusp12 (53% identical). Paralogues in human: SSH2 (24% identical), SSH1 (23% identical), DUSP16 (22% identical), SSH3 (21% identical), DUSP8 (19% identical), STYXL2 (18% identical), DUSP4 (17% identical), DUSP5 (17% identical), DUSP15 (17% identical), DUSP1 (17% identical), DUSP6 (16% identical), DUSP22 (16% identical), and 19 more.
Diseases named in the same sentence as DUSP12 in open-access papers:
DUSP12 is named in the same sentence as 31 diseases in open-access papers, as found by Europe PMC text mining. Sharing a sentence is not in itself a finding about the gene and the disease. The quoted sentences say what the papers report.
neuroblastoma (4 papers, 2016 to 2024). Neuroblastoma (NB) is the most common solid, extracranial childhood tumor. "Later on, the same group reported that common variants in BARD1 gene were associated with high-risk neuroblastoma, and polymorphisms within DUSP12, DDX4, IL31RA, and HSD17B12 were associated with low-risk neuroblastoma." (PMID 31341530, 2019).
breast carcinoma (2 papers, 2015 to 2024). "Using an engineered metastatic niche, we identified a 9‐gene signature (Dhx9, Dusp12, Fhl1, Ifitm1, Ndufs1, Pja2, Slc1a3, Soga1, Spon2) that successfully delineated metastatic breast cancer from nonmetastatic breast cancers including an invasive cell line without metastatic potential." (PMID 38193115, 2024).
Hepatic steatosis (2 papers, 2021 to 2022). Steatosis is a term used to denote lipid accumulation within hepatocytes. "DUSP12-expressed hepatocytes are less inflamed and cause less hepatic steatosis than DUSP12-deleted hepatocytes." (PMID 34414037, 2021). "DUSP9 and DUSP12 retards ASK1 phosphorylation, thereby suppressing MAPKs phosphorylation and subsequent inflammation inhibition, consequently ameliorating hepatic steatosis progression." (PMID 36209205, 2022). "According to our current findings, previous studies, and the characteristic of DUSPs family, we demonstrated that the dephosphorylating capacity of DUSPs family members (DUSP22, DUSP3, DUSP9, DUSP12, DUSP14, DUSP26, etc) might be indispensable for its protective role against hepatic steatosis." (PMID 36209205, 2022).
liposarcoma (2 papers, 2011 to 2022). A usually painless malignant tumor that arises from adipose tissue. "This is of particular importance, as all steps of protein synthesis are susceptible to dysregulation during cancer development, and the overexpression of DUSP12 (the human ortholog of YVH1) has been identified as a candidate oncogene in human liposarcomas." (PMID 36009873, 2022).
Obesity (2 papers, 2011 to 2013). Accumulation of substantial excess body fat. "Therefore, Dusp12 might play a role in the regulation of glycolysis during the early stages of obesity." (PMID 23555558, 2013).
sarcoma (2 papers, 2005 to 2011). A usually aggressive malignant neoplasm of the soft tissue or bone. "ATF6 and DUSP12 seem to be the most likely candidate target genes for the 1q23 amplification in sarcomas." (PMID 16274472, 2005). "Based on their consistent association with this amplicon and possible roles in promoting cell growth, both ATF6 and DUSP12 represent interesting candidate target genes for the 1q23 amplification in sarcomas." (PMID 16274472, 2005).
autoimmune disease (1 paper, 2019). A disorder resulting from loss of function or tissue destruction of an organ or multiple organs, arising from humoral or cellular immune responses of the individual to their own tissue constituents. "Besides DUSP22 downregulation in SLE patients, other DUSPs (DUSP2, DUSP7, DUSP10, and DUSP12) are also downregulated or mutated in human autoimmune diseases." (PMID 31766293, 2019). "DUSP2, DUSP4, DUSP7, DUSP10, DUSP12, DUSP22, and DUSP23 are involved in human autoimmune diseases, including SLE." (PMID 31766293, 2019). "In addition, DUSPs are also involved in either human autoimmune diseases (DUSP2, DUSP7, DUSP10, and DUSP12) or T-cell activation (DUSP1, DUSP5, and DUSP14)." (PMID 31766293, 2019).
chordoma (1 paper, 2025). Chordomas are rare malignant tumors arising from embryonic remnants of the notochord in axial skeleton. "Conversely, overexpression of DUSP12 reduced stemness marker expression and inhibited chordoma cell proliferation." (PMID 40135815, 2025). "Unsurprisingly, our results revealed that deletion of DUSP12 increased the expression of stemness markers and promoted the proliferation of chordoma cells." (PMID 40135815, 2025). "In view of the tumorigenic roles of RAB3B in chordoma and above‐mentioned regulation of RAB3B/DUSP12 in mTORC1 signaling, we further explored the roles of DUSP12 in the stemness and tumorigenesis of chordoma." (PMID 40135815, 2025).
hepatocellular carcinoma (1 paper, 2021). A malignant tumor that arises from hepatocytes. "However, the pathological role of DUSP12 in hepatocellular carcinoma (HCC) is incompletely understood." (PMID 34414037, 2021).
Listeria Infection (1 paper, 2017). "Together, these results suggest that DUSP12 inhibits inflammatory mediator expression in macrophages during Listeria infection through attenuation of p38, and to a lesser extent, JNK activation." (PMID 29062315, 2017). "This demonstrates a negative role of DUSP12 in regulating macrophage responses against Listeria infection." (PMID 29062315, 2017). "We found that the production of proinflammatory cytokines, TNF-α, IL-6 and MCP-1, were impaired in the DUSP12 overexpressing cells, associated with reduced activations of p38 and JNK, but not ERK activation in response to LPS stimulation, BCG, and Listeria infection." (PMID 29062315, 2017).
liver cancer (1 paper, 2021). An epithelial or non-epithelial malignant neoplasm that arises from the liver. "Furthermore, we explored mRNA expression of DUSP12 in patients with different immune-subgroup liver cancer using the TISIDB." (PMID 34414037, 2021). "A PPI network containing DUSP12 and 20 genes in liver-cancer samples in HCCDB was constructed." (PMID 34414037, 2021). "Analyses of functional enrichment of genes co-expressed with DUSP12 in liver-cancer tissues using Metascape showed that these genes were engaged mainly in “histone methylation”, “cullin RING ubiquitin ligase complexes”, “nuclear specks” and “ubiquitin-like protein transferase activity”." (PMID 34414037, 2021). "Integrative analyses of HCCDB revealed that mRNA expression of DUSP12 was higher in liver-cancer tissue compared with that in normal liver tissue in 11 cohorts." (PMID 34414037, 2021). "Human liver-cancer cells (Huh-7) were transfected with a specific shRNA for DUSP12 (shDUSP12) and a nonspecific shRNA (NC)." (PMID 34414037, 2021).
liver fibrosis (1 paper, 2022). "Among all these analyzed DUSPs, DUSP3, DUSP8, DUSP12, DUSP14, DUSP16, DUSP22, and DUSP26 were significantly decreased in the liver of NASH patients with obvious hepatocyte ballooning, severe inflammatory infiltrate, and pattern of liver fibrosis compared with the normal individuals." (PMID 36209205, 2022).
psoriasis (1 paper, 2015). An autoimmune condition characterized by red, well-delineated plaques with silvery scales that are usually on the extensor surfaces and scalp. "Of particular importance was the DUSP12 (dual specificity phosphatase 12) gene; harbouring one homozygous novel mutation in a MAS patient affected by AITD, RA and SS, as well as a second heterozygous novel mutation in another MAS individual (diagnosed with Psoriasis, RA and SS)." (PMID 26031516, 2015).
retinal disease (1 paper, 2012). "Based on putative function and/or involvement in retinal disease, we selected 16 genes – Bach2, Cdr2, Dusp12, Esrrb, Gpsm2, Haus1, Kdm5b, Lman1, Lrp11, Lrrc2, Ncoa2, Plekha2, Ppargc1b, Trim36, Wisp1 and Zdhhc14." (PMID 22511886, 2012).
tuberculosis (1 paper, 2017). A chronic, recurrent infection caused by the bacterium Mycobacterium tuberculosis. "With widespread incidences of multidrug resistant tuberculosis and limitations in novel tubercular drug discovery, DUSP12 may potentially serve as a target for drug development." (PMID 29062315, 2017).
type 2 diabetes (1 paper, 2011). "Studies in Pima Indian, Caucasians and African Americans identified several SNPs in DUSP12 and ATF6, located in chromosome 1q21-q23, were associated with type 2 diabetes." (PMID 21211013, 2011). "Therefore, we performed the present study, aiming to test if variants from DUSP12 and ATF6 played a role in the genetic susceptibility of type 2 diabetes in the Chinese." (PMID 21211013, 2011).
tumor (5 papers, 2005 to 2024). "The correlation between DUSP12 expression and tumor-infiltrating immune cells was demonstrated using the Tumor Immune Estimation Resource database and the Tumor and Immune System Interaction Database." (PMID 34414037, 2021). "DUSP12 expression was positively correlated with the abundance of tumor-infiltrating CD4+ T cells, macrophages, neutrophils, dendritic cells, and expression of the immune-checkpoint moieties HARVC2, TIGIT, CTLA4 and PDCD1." (PMID 34414037, 2021). "DUSP12 was expressed significantly higher than ATF6 in these two tumours (p < 0,001 for MS8x and p < 0,01 for LS21), and also in LMS2x and MFH19 (both p < 0,001)." (PMID 16274472, 2005). "LMS15 and LS43 showed the same expression levels of both ATF6 and DUSP12 as the tumours with normal copy number of the genes." (PMID 16274472, 2005). "LS3x showed 3-fold over-expression of both genes, and for LMS2x and MFH19, DUSP12 was over-expressed 2–3 fold whereas ATF6 was expressed at the same level as the three tumours with normal copy number." (PMID 16274472, 2005). "Furthermore, Dhx9, Dusp12, Fhl1, and Ifitm1 are each correlated with the invasion of tumor‐infiltrating immune cells into the microenvironment." (PMID 38193115, 2024). "Since DUSP12 may be involved in cell proliferation, it is possible that amplification of DUSP12 stimulates tumour growth." (PMID 16274472, 2005). "DUSP12 was expressed significantly higher than ATF6 in a subset of the tumours." (PMID 16274472, 2005). "Thus, except for LS3x, DUSP12 is significantly higher expressed than ATF6 in all the tumours that showed at least 2-fold over-expression of either or both genes, suggesting that DUSP12 may be the real target for the amplification." (PMID 16274472, 2005). "For tumours LS3x, LS21, LS43 and MS8x, the genes ATF6 and DUSP12 showed the highest amplification level in general, 3–5 fold in LS3x and 5–10 fold in LS21 and LS43 (except ATF6), and particularly high copy numbers (>10 fold) in MS8x." (PMID 16274472, 2005). "DUSP12-altered patients had a higher serum level of alpha fetoprotein (AFP) at procurement, fraction of genome altered and worse histology grade in neoplasms." (PMID 34414037, 2021). "For tumours LS3x, LS21, LS43 and MS8x, the genes ATF6 and DUSP12 showed the highest amplification level in general, suggesting that one of them may be the target for this amplification." (PMID 16274472, 2005). "The expression levels of ATF6 and DUSP12 were determined by quantitative real-time RT-PCR, and in general the expression level of ATF6 and DUSP12 reflected the amplification level in the different tumours." (PMID 16274472, 2005). "DUSP12 seems to be the most likely target based on the significantly higher expression in a subset of the tumours, but since relevant genes activated by ATF6 also are highly expressed in tumours with over-expression of ATF6, both genes are considered potential targets." (PMID 16274472, 2005).
cancer (4 papers, 2011 to 2024). A tumor composed of atypical neoplastic, often pleomorphic cells that invade other tissues. "The nine genes identified in our signature (Dhx9, Dusp12, Fhl1, Ifitm1, Ndufs1, Pja2, Slc1a3, Soga1, and Spon2) have each been investigated for their role in cancer." (PMID 38193115, 2024).
bacterial infection (1 paper, 2017). "Next, we selected another overexpressing clone (OXE), which has DUSP12 levels of approximately three to four times that of the control cells, to verify the function of DUSP12 in macrophages in response to intracellular bacterial infection." (PMID 29062315, 2017). "Thus, DUSP12 is a bona fide MAPK phosphatase, playing an important role in MAPK-regulated responses to bacterial infection." (PMID 29062315, 2017). "Overexpression of DUSP12 suppressed the production of various proinflammatory cytokines and chemokines upon TLR activation or intracellular bacterial infection by L. monocytogenes or Mycobacterium bovis BCG by inactivating JNK and p38, and defective killing of intracellular pathogens." (PMID 29062315, 2017). "The binding of DUSP12 to p38 is the weakest among the three MAPKs, yet DUSP12 has the strongest inhibition toward the activation of p38 compared with that of JNK or ERK in macrophages upon TLR activation or intracellular bacterial infection." (PMID 29062315, 2017). "In addition, overexpression of DUSP12 in macrophages suppressed p38 and JNK activation in response to TLR4 stimulation or intracellular bacterial infection." (PMID 29062315, 2017). "Interestingly, immunoprecipitation data showed that the interaction between DUSP12 and p38 is the weakest as compared to JNK or ERK, but it is apparent that DUSP12 mainly suppresses the activation of p38 in macrophages during intracellular bacterial infection." (PMID 29062315, 2017).
infection (1 paper, 2017). The state of being infected such as from the introduction of a foreign agent such as serum, vaccine, antigenic substance or organism. "In summary, this study demonstrates that DUSP12 is a p38 and JNK phosphatase, where modulation in MAPKs activation leads to impairment of proinflammatory cytokine and chemokine production in macrophages upon TLR activation or pathogen infection." (PMID 29062315, 2017).
DUSP12 also shares sentences with these, for which no sentence is quoted: malaria (2 papers); Autoimmunity (1); breast adenocarcinoma (1); cervical adenocarcinoma (1); dependence (1); diabetes (1); fibrosarcoma (1); Hypertension (1); liver diseases (1); neurodegenerative disease (1); nonalcoholic steatohepatitis (1).